STAT6 (signal transducer and activator of transcription 6)
Diseases named in the same sentence as STAT6 in open-access papers (continued):
Sharing a sentence is not in itself a finding about the gene and the disease.
penile cancer (1 paper, 2024). A primary or metastatic malignant neoplasm that affects the penis. "During malignant progression phase of penile cancer, the expression evolution of JAK-STAT-SOCS1 axis was characterized by the upregulation of JAK1, JAK3, STAT4, STAT5A and STAT6." (PMID 38774752, 2024).
peripheral nerve injury (1 paper, 2017). Injury to a peripheral nerve. "For example, IL-4 was shown to promote motor neuron survival through STAT6 signaling in a model of peripheral nerve injury, while in dorsal root ganglion cells, IL-4 enhanced axonal regeneration through the stimulation of local neurotrophin secretion." (PMID 29064422, 2017).
peripheral T-cell lymphomas (1 paper, 2020). "We also found mutations in NOTCH1/NOTCH2 and JAK/STAT genes, previously reported to be mutated in peripheral T-cell lymphomas: NOTCH1 (16/71, 22%), NOTCH2 (14/71, 19%), JAK3 (5/71, 7%), and STAT6 (2/71, 3%)." (PMID 31028364, 2020).
psychosis (1 paper, 2008). "Therefore, we are only able to state that STAT6 has a tendency to be associated with periodic psychosis." (PMID 20046407, 2008). "In schizophrenic brain, showing progressive recession, we hypothesized that STAT6, which is located down-stream in the apoptotic cascade, might be a cause of periodic psychosis." (PMID 20046407, 2008). "The current investigation may potentially explain the mechanism of periodic onset of psychosis, although future work will be needed to reveal the etiological role of STAT6 at the molecular level." (PMID 20046407, 2008).
pulmonary hypertension (1 paper, 2021). Increased pressure within the pulmonary circulation due to lung or heart disorder. "In a hypoxia-induced pulmonary hypertension model, Th2 regulation did not play a role since IL-4 and STAT6-deficient mice had the same HIMF expression levels as wild-type mice." (PMID 33800244, 2021). "The roles of IL-4 and STAT6 are also critical to HIMF-mediated pulmonary hypertension." (PMID 33800244, 2021).
renal carcinoma (1 paper, 2022). A carcinoma arising from the epithelium of the renal parenchyma or the renal pelvis. "To detect whether these signaling pathways were required for IFI35-mediated autophagy, we first detected phosphorylated expression levels of STAT1/STAT6 in IFI35 shRNA-treated renal cancer cells." (PMID 35740527, 2022). "Additionally, blockade of STAT1/STAT6 phosphorylation (pSTAT1/pSTAT6) abrogated the induced autophagy by IFI35 knockdown in renal cancer cells." (PMID 35740527, 2022). "Knockdown of IFI35 could inhibit the proliferation and invasion of renal cancer cells by enhancing the STAT1/STAT6 phosphorylation (pSTAT1/pSTAT6)-dependent autophagy." (PMID 35740527, 2022). "The results demonstrated that knockdown of IFI35 could inhibit the proliferation and invasion of renal cancer cells by enhancing the STAT1/STAT6 phosphorylation (pSTAT1/pSTAT6)-dependent autophagy." (PMID 35740527, 2022).
renal clear cell carcinoma (1 paper, 2025). "In renal clear cell carcinoma, SIRT6 deacetylates STAT6 at lysine 284, thereby modulating the AF9/STAT6 signaling axis that governs purine metabolism and apoptosis." (PMID 41463311, 2025).
Renal cyst (1 paper, 2021). A fluid filled sac in the kidney. "While, during the progression of ADPKD, the cleaved PC1 tail could co-activate STAT1 that had been activated by IFN, STAT3 that had been activated by IL-6, EGF, HGF (hepatocyte growth factor) signaling, STAT6 that had been activated by IL4, IL-13 signaling to promote renal cyst growth and fibrosis." (PMID 34199002, 2021). "Genetic knockout of STAT3 and STAT6, STAT3 inhibitor S3I-201, STAT6 non-specific inhibitor teriflunomidelysine, methyltransferase SMYD2 specific inhibitor AZ505, or anti-parasitic compound pyrimethamine could attenuate ADPKD cell proliferation and reduce renal cyst formation." (PMID 34199002, 2021).
rhinosinusitis (1 paper, 2022). "However, STING represses IL-13-induced STAT6 phosphorylation in subjects with rhinosinusitis by increasing expression of the STAT6 inhibitor SOCS1 (suppressor of cytokine signaling 1)." (PMID 35281022, 2022).
schizophrenia (1 paper, 2015). A major psychotic disorder characterized by abnormalities in the perception or expression of reality. "Interestingly, STAT6 is among the immunological genes that were significantly associated with schizophrenia in the largest genome-wide association study of schizophrenia published to date." (PMID 25970596, 2015). "The largest genome-wide association study of schizophrenia to date shows further support for the role of immunological factors in the pathogenesis of symptoms: genes expressed in the immune cells, such as STAT6 and TCF4, were overrepresented in the genetic loci associated with schizophrenia." (PMID 25970596, 2015).
scleroderma (1 paper, 2022). Scleroderma is a rare autoimmune connective tissue disorder characterized by abnormal hardening of the skin and, sometimes, other organs. "CD8+ T cells had infiltrated the skin of patients with scleroderma, particularly in the early stage, and their cytokine IL-13 promoted the activation of signal transducer and activator of transcription 6 (STAT6) signal through highly expressed receptors in the monocytes and fibroblasts." (PMID 35185577, 2022).
spindle cell rhabdomyosarcoma (1 paper, 2021). An uncommon variant of rhabdomyosarcoma characterized by the presence of whorls of spindle cells forming a storiform pattern. "Immunohistochemical analysis showed negative staining with Cytokeratin, S100, CD34, Stat6, h-Caldesmon and EMA while the tumour cells were positive for desmin, myogenin, smooth muscle actin, CD-99 and MyoD1 thus confirming the diagnosis of spindle cell rhabdomyosarcoma." (PMID 34104191, 2021).
squamous cell lung carcinoma (1 paper, 2019). A carcinoma arising from squamous bronchial epithelial cells. "STAT6 is highly expressed in 54–55% of NSCLC, and the negative regulator of STAT6-suppressor of cytokine signaling-3 is reduced in squamous cell lung carcinoma." (PMID 31798581, 2019).
tapeworm infections (1 paper, 2022). "McKay and Khan (2003) examined the effect of H. diminuta tapeworm infections in mice with knockout IL-4, IL-13 and STAT-6 (signal transducer and activator of transcription 6) genes." (PMID 36558772, 2022).
urticaria (1 paper, 2023). A vascular reaction of the skin characterized by erythema and wheal formation due to localized increase of vascular permeability. "For variants at the FCER1A and the STAT6 loci, the allele that associates with lower risk of urticaria also associates with decreased serum IgE levels and both are highly correlated with variants previously reported to associate with serum IgE levels (r2 of 0.87 and 1.00, respectively) 20,21." (PMID 37430141, 2023).
vasculitis (1 paper, 2021). "Because IL5Tg mice on ILC2del, STAT6–/– or IL4Rα–/– backgrounds had severe hypereosinophilia but few pulmonary intraparenchymal eosinophils and no vasculitis, we suspected that IL4Rα signaling might promote eosinophil migration into tissue." (PMID 33974563, 2021).
Zinc deficiency (1 paper, 2017). A deficiency of the essential metal Zinc; an essential cofactor for many enzymes. "Zinc supplementation decreased STAT6 phosphorylation reducing the amount of M2 macrophages, while zinc deficiency increased phosphorylation of STAT2, thereby supporting M1 development." (PMID 29064429, 2017). "On a molecular mechanism this might be due to diminished STAT6 phosphorylation during zinc deficiency." (PMID 29064429, 2017).
tumor (485 papers, 2002 to 2026). "QRHXF enhanced antitumor immune responses in NSCLC via TREM2 and modulation of the PI3K/AKT/STAT6 signaling pathway, reducing chemotactic infiltration of M2 tumor-associated macrophages within the TME." (PMID 40670983, 2025). "In a B16 melanoma model, TRAF3 deficiency in bone marrow suppressed tumor growth and metastasis, underscoring STAT6’s importance in macrophage-mediated immunosuppression." (PMID 40079009, 2025). "After removal of the primary tumor, STAT6-deficient mice rejected liver metastasis and lived longer than WT mice in the same conditions." (PMID 41409600, 2025). "More surprisingly, low-inorganic phosphate stress irreversibly repolarized tumor-associated macrophages towards the M1 phenotype by silencing STAT6 and activating the p65 subunit of NFκB." (PMID 41409600, 2025). "The activation of the JAK1/STAT6 pathway was found to be associated with tumor progression and M2 polarization." (PMID 40604704, 2025). "Tumor‐associated macrophages (TAMs), constituting 30%–50% of the tumor immune microenvironment, drive tumor progression through the STAT6/PPARγ axis‐mediated polarization into the M2 phenotype." (PMID 41360672, 2025). "In tumor-associated macrophages, the acetylation of the transcription factor STAT6 affects their ability to kill tumor cells." (PMID 40563863, 2025). "Th2 cells complement this by activating the IL-4/Gata3/STAT6 axis, inducing genes linked to proliferation and metastasis, and promoting integrin-mediated tumor invasion." (PMID 40510347, 2025). "The unique role of STAT6 in the polarization of macrophages to the M2 phenotype, which is associated with tumor progression, should be emphasized." (PMID 39936166, 2025). "In particular, the JAK/STAT signaling pathway is a driver of tumor development due to multiple recurrent mutations, particularly in STAT6." (PMID 38773631, 2024). "Further, in line with our findings, adjuvant medicines were shown to significantly slow tumor growth when used in combination with 5-FU, which was linked to a reduction in STAT6-phosphorylation." (PMID 38419894, 2024). "Cytokines such as IL-4 and IL-13 within the tumor microenvironment regulate the polarization of tumor-associated macrophages (TAMs) through downstream Stat6-dependent inhibition of Arg1, activation of PPARγ, and TSC1-mediated inhibition of mTOR." (PMID 39676873, 2024). "Site mutation analysis revealed that ubiquitination at STAT6 K450 plays a crucial role in TRAF3-mediated STAT6 activation, which promotes increased expression of M2-associated surface markers as well as tumor progression." (PMID 39403370, 2024). "For example, exoASO-STAT6 uses ECVs to deliver antisense oligonucleotides that disrupt STAT6 signaling in tumor-associated macrophages." (PMID 39061191, 2024). "Conversely, activation of STAT3 and STAT6 by IL-4 and IL-13 predominantly leads to polarization of macrophages towards the M2 phenotype, associated with immune suppression and tumor progression." (PMID 38745331, 2024). "YY1 function is regulated through the IL-4/STAT6 signaling pathway in tumor-associated immune cells." (PMID 37762277, 2023). "We demonstrate that AAP/NAC inhibits IL-4/STAT6 signaling, and the resulting M2 polarization, in tumor-associated macrophages." (PMID 37835464, 2023). "In line with our observation, several studies have demonstrated that STAT6 is highly expressed in several types of cancer and that CRC cells especially exhibit a high STAT6 activity, which is associated with increased invasion, tumor growth, and metastasis." (PMID 38201452, 2023). "An engineered exosome has been developed to deliver an antisense oligonucleotide (ASO) targeting STAT6 (exoASO-STAT6), which selectively silences the expression of STAT6 in tumor-associated macrophages (TAMs)." (PMID 37514088, 2023).
tumor (continued). "One example is exoASO-STAT6, a precision drug candidate that uses EVs to selectively deliver antisense oligonucleotides to disrupt STAT6 signaling in tumor-associated macrophages (TAM) and induce antitumor immune responses." (PMID 37763719, 2023). "Among five cancer-associated STAT6 missense variants, three of them (i.e. p.D419G, p.D419N, and p.D523V) were present in both cfDNA and tumor tissue DNA in FL patients." (PMID 35795062, 2022). "Low STAT6 expression was associated with histological type, residual tumor of UCEC, histological grade, and median survival age of UCEC." (PMID 35244291, 2022). "TAM inhibits PA progression by inducing apoptosis and expression changes of apoptosis-related proteins, and reprogramming tumor-associated macrophages to the M1 phenotype via STAT6 inactivation and SHP1/SHP2 blockade." (PMID 35269804, 2022). "The same behavior happens when the M2-associated transcription factors are disturbed (STAT3 or STAT6); cycle attractors will prevent a hyper-regulation scenario implicated in providing a suitable environment for tumor growth." (PMID 36544764, 2022). "Loss of STAT6 phosphorylation leads to the downregulation of PD-L2 on tumor cells and DCs and, in turn, increases tumor recognition by T lymphocytes." (PMID 36003765, 2022). "In another study, increased expression of IL‐4/STAT6 signaling was associated with reduced tumor volume and weight, as well as the increased expression of apoptotic proteins." (PMID 35244291, 2022). "Another engineered exosome is exoASO-STAT6 that uses the same scaffold but to, instead, attach an antisense oligonucleotide, which is designed to silence STAT6, a transcription factor for tumor-associated macrophages that promotes cancer progression." (PMID 35159299, 2022). "The STAT6 gene mutations (and other most frequent mutations) were already detectable in the so-called ancestral clones forming the initial tumor at diagnosis." (PMID 36074181, 2022). "In the present study, we evaluated the frequency of peripheral and local Treg cells in the course of CAC during STAT6 deficiency and analyzed the effect of Treg cells depletion in the early stages of tumor progression." (PMID 33919941, 2021). "With STAT6 deficiency, increased Treg populations induce resistance against tumor-promoting inflammation, and tumorigenesis is therefore stopped." (PMID 33919941, 2021). "AOM/DSS administration resulted in a significant decrease in inflammation and tumor development under STAT6 deficiency." (PMID 33919941, 2021). "Recently, Binnemars-Postma and colleagues report that inhibition of STAT6 with AS1517499 attenuates tumor associated macrophages into M2 phenotypes and reduces tumor growth and metastasis." (PMID 34512669, 2021). "STAT6 is a factor converge on intracellular determinants of cell functions and drives the recruitment and polarization of tumor-associated macrophages (TAMs)." (PMID 33274204, 2020). "In conclusion, these results indicated that these five risk genes (CD19, FGF2, MAP4K1, DCN and STAT6) were actually differentially expressed between normal kidney samples and ccRCC tumour samples." (PMID 31782902, 2020). "A previous study indicated that the expression of STAT6 signal was down-regulated during the differentiation of tumor-associated neutrophils from CD11b+Gr-1+ IMCs of HDC-KO mice." (PMID 33192584, 2020). "In primary and metastatic mammary carcinomas, the deficiency of STAT6 correlates with enhanced tumor immunity and the faster rejection of implanted tumors." (PMID 32244885, 2020). "The reduced differentiation to M2 macrophages in STAT6-deficient mice indicates that macrophage polarization contributes to a suppressed tumor growth state." (PMID 31798581, 2019). "Our results indicate that STAT6 deficiency inhibits carcinogen-induced tumor growth and improves prognosis." (PMID 31798581, 2019).
tumor (continued). "The seeming opposing results showing enhanced cytotoxicity of IL-4/STAT6-activated as well as STAT6-deficient NK cells certainly call for a more detailed analysis of the role of STAT6 in NK cells in the context of anti-tumor and anti-viral immunity." (PMID 31781102, 2019). "Tumor-associated IL-4 can induce Th2 differentiation via STAT6 phosphorylation to directly inhibit T-cell cancer immunity." (PMID 31379876, 2019). "Conversely, tumor associated macrophages (TAMs) from the STAT6-null mice showed a functional M1 phenotype upon activation as characterized by i.e. NO production, which firmly indicated that JAK1, 3/STAT6 signaling pathway are essential for the M2 activation." (PMID 28948005, 2017). "STAT6 is also associated with M2 polarization and STAT6−/− mice showed less tumor growth and metastasis due to enhanced CD8+ Th1 response." (PMID 28197019, 2017). "Reduction of numbers and functions of tumor-infiltrating ISCs due to changes in the tumors' cytokine milieu and decreased STAT6 signaling in ISCs was identified as one of the underlying mechanism." (PMID 26943036, 2016). "A predominance of STAT3 and STAT6 activation results in M2 macrophage polarization, associated with immune suppression and tumor progression." (PMID 24574581, 2013). "Tumor-associated endothelial cells, which frequently displayed high intensity staining of STAT6, were disregarded when describing a sample as STAT6 positive or negative." (PMID 21595984, 2011). "Moreover, mutations in STAT3 and STAT6 are known to increase PD-L1 expression and enhance the production of tumor-associated antigens." (PMID 40243506, 2025). "Furthermore, the expression level of STAT6 was significantly associated with tumor size and high histological grades of PCa." (PMID 38877472, 2024). "Importantly, TGR5 activated the cAMP-STAT3/STAT6 axis to promote M2 polarization of tumor-associated macrophages and suppress CD8+ T-cell anti-tumor immunity in non-small-cell lung cancer mouse models." (PMID 37686465, 2023). "In tumor environment, the miR-449c/STAT6 axis is associated with the expansion of M-MDSCs, thus, blocking miR-449c axis may offer an effective epigenetic therapy to inhibit tumor progression." (PMID 36439186, 2022). "Furthermore, tamoxifen also inhibited the migration of both cell lines by reprogramming tumor-associated macrophages to the M1 phenotype through STAT6 inactivation and inhibition of the macrophage-specific immune checkpoint SHP1/SHP." (PMID 35269804, 2022). "Moreover, tissue analysis of PCa and normal prostate linked STAT6 expression to high-grade PCa tissues (Gleason score ≥ 4 + 3) and larger tumor size." (PMID 34638338, 2021). "In a future study, we could test this idea by investigating the effect of ICJ on STAT6 genetically deficient mice and its association to macrophage polarization in tumor burden mice." (PMID 35027915, 2021). "Recently, STAT6 signaling has been associated with the initiation of malignant transformation and tumor establishment, and STAT6-phosphorylation has frequently been found in malignant cells that regulate several genes crucial for the immune response and proliferation." (PMID 33919941, 2021). "Additionally, several miRNAs were found acting as tumor suppressors while suppressing tumor growth, inducing apoptosis, or inhibiting metastasis in PCa by targeting STAT6, thereby underlining the cancer-promoting functioning of STAT6 in PCa." (PMID 34638338, 2021). "STAT6 is associated with the regulation of the lipid metabolism, our macrophages can obtain energy from lipids to liberate cytotoxic interleukins and eliminate tumor cells." (PMID 34177892, 2021). "In recent years, some studies have pointed out that immunohistochemical analysis showed that not only CD34 and Bcl2 are positive in tumor cells, but also nuclear STAT6 is positive, indicating that the tumor may be a rare variant of SFT." (PMID 33499815, 2021).